IL22 (interleukin 22)
Description:
Cytokine that plays a critical role in modulating tissue responses during inflammation. Plays an essential role in the regeneration of epithelial cells to maintain barrier function after injury and for the prevention of further tissue damage. Unlike most of the cytokines, has no effect on immune cells. Signals through a heterodimeric receptor composed of two subunits, the specific receptor IL22RA1 which is present on non-immune cells in many organs and the shared subunit IL10RB. Ligation of IL22RA1 with IL22 induces activation of the tyrosine kinases JAK1 and TYK2, which in turn activates STAT3. In turn, promotes cell survival and proliferation through STAT3, ERK1/2 and PI3K/AKT pathways. Promotes phosphorylation of GSK3B at 'Ser-9' and CTTN (By similarity). Promotes epithelial cell spreading (By similarity).
Synonyms: IL-22; IL-TIF; ILTIF; ZCYTO18; IL-21; IL-D110; TIFa; TIFIL-23; MGC79382; MGC79384
Tractability: Small molecule: a structure with a bound ligand is known. Antibody: a drug acting on it is in phase 2 or 3 trials; its Gene Ontology location is reachable by antibodies, with high confidence; UniProt places it where antibodies can reach, with medium confidence; UniProt predicts a signal peptide or a membrane-spanning region.
Target class: Secreted protein
Gene: Protein-coding gene on chromosome 12 (68,248,242 to 68,253,604, reverse strand). Ensembl gene ENSG00000127318.
Subcellular location: Secreted
Pathways (Reactome):
Disease: Signaling by ALK fusions and activated point mutants
Immune System: Interleukin-20 family signaling
Gene Ontology:
Molecular function: protein binding; cytokine activity; interleukin-22 receptor binding
Biological process: acute-phase response; inflammatory response; negative regulation of inflammatory response; response to glucocorticoid; signal transduction
Cellular component: decoy receptor complex; receptor complex; extracellular region
Genetic constraint (gnomAD): Loss-of-function variants: 12 observed, 12.64 expected, observed/expected ratio (o/e) 0.95, 90% interval 0.61 to 1.53. The upper end of that interval is the gene's LOEUF score, 1.53, which puts it in group 6 of 6, group 1 being the genes least tolerant of losing a copy. Missense variants: 166 observed, 170.51 expected, observed/expected ratio (o/e) 0.97, 90% interval 0.86 to 1.11. Synonymous variants: 71 observed, 65.98 expected, observed/expected ratio (o/e) 1.08, 90% interval 0.89 to 1.31.
Homologues: Orthologues: chimpanzee IL22 (99% identical), macaque IL22 (96% identical), dog IL22 (91% identical), rabbit IL22 (79% identical), mouse Il22 (78% identical), mouse Il22b (78% identical), guinea pig IL22 (77% identical), pig IL22 (75% identical), rat Il22 (75% identical), tropical clawed frog IL22 (33% identical).
Diseases named in the same sentence as IL22 in open-access papers:
IL22 is named in the same sentence as 551 diseases in open-access papers, as found by Europe PMC text mining. Sharing a sentence is not in itself a finding about the gene and the disease. The quoted sentences say what the papers report.
psoriasis (700 papers, 2009 to 2026). An autoimmune condition characterized by red, well-delineated plaques with silvery scales that are usually on the extensor surfaces and scalp. "The expression of CDC6 is regulated by IL-22, one of the important cytokines implicated in the pathogenesis of psoriasis." (PMID 39846685, 2025). "In psoriasis, tapinarof reduces the levels of key pathogenic cytokines, including IL-17A, IL-17F, IL-22, and IL-23." (PMID 40162433, 2025). "Specifically, studies have found that Ligilactobacillus and Anaeroplasma correlate positively with psoriasis-associated cytokines IL-6, IL-17A, IL-22, and IL-23, while Rikenella, Alistipes, and Mucispirillum are negatively correlated." (PMID 40161116, 2025). "Given their known pathogenic role of secreting IL-22 in response to IL-23, NK-22 cells are likely also implicated in psoriasis, though this has yet to be confirmed." (PMID 40873573, 2025). "Human psoriasis is predominantly caused by the IL-23/Th17 axis, with Th17 cells generating pro-inflammatory cytokines including IL-17 and IL-22, which play an important role in inflammation and tissue destruction." (PMID 40667480, 2025). "Biopsy specimens from plaques of psoriasis vulgaris demonstrate increased levels of IL-17 in association with increased expression of IL-23 and IL-22, whereas serum levels of IL-17 are associated with psoriasis severity." (PMID 40906403, 2025). "The activated immune cells produce large numbers of pro-inflammatory mediators, including IL-17, TNF-α, and IL-22, which in turn result in the activation of keratinocytes and form a positive feedback loop, eventually causing the expansion of psoriasis plaques." (PMID 40108109, 2025). "It has been shown that several cytokines were associated with psoriasis, including TNFα and IL-22, which both, either alone or in combination, promote IL-36 production by primary human keratinocytes and organotypic skin models." (PMID 40563994, 2025). "AD is classically associated with dysregulation of the Th2 subset (IL-4, IL-5, IL-13, and IL-31), whereas the Th17 subset (IL-17, IL-21, and IL-22) has been implicated in the pathogenesis of psoriasis." (PMID 40535962, 2025). "It was shown by our group and others that the psoriasis-associated cytokines IL-17 and IL-22 are suited to mimic psoriatic characteristics in 3D in vitro models." (PMID 40678130, 2025). "Th22 cells were found to be increased in the skin of psoriasis patients, and a deficiency in the Th22 cytokine IL-22 was found to decrease skin thickening and inflammation." (PMID 39337637, 2024). "In a study of AHR-deficient mouse models, the mice demonstrated increased IL-22 and IL-17 cytokines, as well as psoriasis-like skin inflammation." (PMID 39337637, 2024). "Group 3 innate lymphoid cells lack rearranged antigen-specific receptors, rely on the transcription factor RORγt, and respond to IL-1β and IL-23; a subset of group 3 innate lymphoid cells is associated with production of IL-17A and IL-22 in psoriasis lesions." (PMID 39114670, 2024). "Serum biomarkers associated with psoriasis and the IL-23/IL-17 and IL-22 immunologic pathways were elevated at baseline and were reduced with guselkumab to a greater extent than with ADA." (PMID 39114670, 2024). "Dysregulated IL-22 levels in tandem with Th17-cell activation and IL-17 activity are implicated as key factors in psoriasis development." (PMID 38892253, 2024). "ILC3s are primarily found in the intestine and skin and are considered to play a pathogenic role in psoriasis by producing IL-17A and IL-22." (PMID 38347543, 2024). "IL22 has been associated with psoriasis risk quantitatively by GWAS: a higher number of IL22 gene copies leads to a higher risk of nail psoriasis." (PMID 38256115, 2024). "Concurrently, this demonstrates that APLNs used in treating IMQ-induced mouse psoriasis can mitigate skin psoriasis in mice through the diminished levels of cytokines associated with psoriasis, including IL-17F, IL-22, and IL-17A etc." (PMID 39534602, 2024).
psoriasis (continued). "Second, IL-17 and IL-22 are related to the etiology of autoimmune diseases such as psoriasis and numerous inflammatory-associated cancers, including CRC47." (PMID 38238429, 2024). "IL-22 can also have effects divergent from those of IL-17 associated with disruption of normal keratinocyte differentiation in psoriasis." (PMID 39114670, 2024). "Psoriasis is largely associated with the activation of T-helper 17 (Th17) cells, which produce pro-inflammatory cytokines such as IL-17 and IL-22." (PMID 39463646, 2024). "A synthetic cytokine converter for mammalian cells was engineered to quantify levels of TNF and Interleukin-22 (IL-22) associated with psoriasis." (PMID 38362504, 2024). "Expression of IL-22 is often associated with inflammatory skin conditions, such as psoriasis, where it is often co-expressed with IL-17A." (PMID 38543790, 2024). "It has been described that the psoriasis-associated cytokines IL-17 and IL-22 promote the secretion of AMPs such as hBD2 and LL-37 by keratinocytes." (PMID 38251799, 2024). "Specific IL-22 genetic variants are associated with altered skin barrier functions, correlating with an early onset and increased severity of psoriasis." (PMID 38892253, 2024). "Psoriasis and atopic dermatitis in humans, conditions characterized by severe itching, have been linked to IL-17/IL-22 producing γδ T-cells." (PMID 39911485, 2024). "Psoriasis is an inflammatory condition that is associated with excessive secretion of proinflammatory cytokines (IL-2, IL-6, IL-8, IL-12, IL-19, IL-22, IL-23, IFN-γ and TNF-α) into blood as well as dermal tissue." (PMID 37266425, 2023). "IL22 has been associated with psoriasis by GWAS, with a quantitative effect: the greater the copy number of the IL-22 gene, the greater the risk of nail disease." (PMID 37628670, 2023). "The recently identified Th22 effector T cell subset, characterized by IL-22 and IL-13 production, has also been implicated in psoriasis." (PMID 37662940, 2023). "Out of those, differentiated TH17 comprises the central pathogenic cell subtype of psoriasis, orchestrating the expression of IL-17A, IL-17F, and IL-22, amongst others." (PMID 37108251, 2023). "Of note, IL-22 has also been found to be a pathogenic cytokine in psoriasis due to the IL-22-promoted excessive regeneration of epithelial cells." (PMID 37217798, 2023). "IL-22 has also been associated with pro-inflammatory activity in several inflammatory diseases such as psoriasis, asthma, ankylosing spondylitis, and atopic dermatitis." (PMID 36875710, 2023). "Their study revealed that the topical application of compound 3 (2 mM) significantly ameliorated hyperplasia and inflammatory cell infiltration and suppressed the expression of the psoriasis-associated genes S100a9, Krt1, Il17a, and Il22." (PMID 37111813, 2023). "It had been demonstrated that curcumin can reduce various inflammatory factors such as TNF‐α, IFN‐γ, IL‐22, and IL‐23 in mouse serum, which are closely involved in the pathogenic mechanism of psoriasis." (PMID 37647442, 2023). "It has emerged that in HS patients, there is a relative deficiency of IL22 expression in the lesional skin compared with other chronic inflammatory skin diseases, such as psoriasis or atopic dermatitis." (PMID 37176138, 2023). "The Th22/IL-22 pathway has a pathogenic function in psoriasis, and evidence suggests that Th22 cells are also involved in psoriasis relapse." (PMID 38239345, 2023). "In the first case, T-helper 17 is implicated in the pathogenesis of psoriasis, and interleukins IL-17, IL-22, and IL-23 are the main cytokines involved." (PMID 36770889, 2023). "Although IL-22 has been associated with the development of autoimmune and inflammatory diseases, such as psoriasis and rheumatoid arthritis, it is a cytokine with dual pro- and anti-inflammatory activities." (PMID 36768762, 2023).
psoriasis (continued). "The production of IL-17A and IL-22, key inflammatory cytokines that are heavily implicated in the pathogenic of psoriasis, by CD4+ T cells has marked CD4+ T cells as a main target of research." (PMID 38067173, 2023). "In children, however, it is reported in the literature that the lesional tissue of patients with pediatric psoriasis is associated with higher levels of TNF-α, IL-22-producing T cells and relatively fewer IL-17-producing T cells compared with adult psoriasis." (PMID 36232430, 2022). "Both circulation and skin lesion showed higher IL-22 expression in psoriasis patients, which was also associated with disease severity." (PMID 35911703, 2022). "As described in the introduction, IL-22 takes part in the pathogenesis of psoriasis as well and apparently, it was the first disease associated with dysregulated secretion of this cytokine." (PMID 36226313, 2022). "IL-22 exerts its pathogenic role in psoriasis by inhibiting the terminal differentiation of keratinocytes, as well as inducing antimicrobial peptides and proinflammatory chemokines." (PMID 35075118, 2022). "In comparison with etanercept, ustekinumab excels in suppressing multivariate psoriasis-associated genes and cytokines such as IL-1, IL-22, IFN-γ and IL-17." (PMID 35203707, 2022). "They introduced Card14ΔE138K/A mutations in mice with psoriasis and found an up-regulation of pro-inflammatory cytokines, IL-23, IL-19, IL-22 and IL-17; chemokines Cxcl1, Ccl20, and Cxcl2; and antimicrobial peptides, Lcn2 and Defb4." (PMID 36012602, 2022). "The IFN-γ, IL-17A and IL-22 are key pathogenic cytokines in psoriasis and one of the main mediators of cytokine signaling is STAT1." (PMID 33986690, 2021). "Lesional tissue from pediatric psoriasis patients is associated with higher levels of IL-22-producing T cells and relatively fewer IL-17-producing T cells compared with adult psoriasis." (PMID 34440145, 2021). "The role of IL-22 in epithelial homeostasis is further underlined by its association to inflammatory skin and gut diseases such as atopic dermatitis, psoriasis and colorectal cancers." (PMID 34408754, 2021). "On the contrary, coexpression of IL-22 and IL-17A has been implicated in the development of proinflammatory processes during inflammatory and autoimmune diseases, such as psoriasis and Crohn's disease." (PMID 34805416, 2021). "The IL-23 is crucial in the pathogenesis of psoriasis and causes Th17 cells to produce IL-17 and IL-22." (PMID 34640327, 2021). "It is demonstrated that IL-22 can increase expression of miR-122-5p, inhibit expression of Spry2, promote proliferation of keratinocytes, and eventually cause occurrence of psoriasis." (PMID 33975513, 2021). "The psoriasis-associated cytokines IL-17A, IL-22 and IFN-γ induce the expression of the transcription factor Nrf2 and subsequently KRT17, eventually leading to hyperproliferation of keratinocytes." (PMID 33801280, 2021). "In vitro stimulation of ILC NCR+ produces IL-22, which is implicated in the pathogenesis of psoriasis, and increases the production of S100 AMPs." (PMID 34884596, 2021). "The changes in the microbiome associated with psoriasis can induce an inflammatory response by activating the cytokines IL-23, IL-17 and IL-22 as well as the modulation of the gamma interferon (IFN-γ) and inhibiting T regulatory cells (Treg) production." (PMID 33924414, 2021). "TNF-α, IFN-γ, IL-17, and IL-22 lead to keratinocyte proliferation which causes increased inflammation and formation of plaques found in psoriasis." (PMID 34884596, 2021). "It has been observed that epidermal expression of STAT3 in a transgenic mouse, activated by the IFN-γ, IL-6, IL-20, IL-17A, and IL-22 cytokines, causes psoriasis." (PMID 34769005, 2021). "Examples are accumulation of granulocytes stimulated by IL-8, IL-17, IL-9 and IL-13; epidermal hyperplasia and psoriasis-like skin lesions due to IL-22; and fever and weight loss in response to IL-6 and IFN-γ." (PMID 34503066, 2021).
psoriasis (continued). "Dysregulated IL-22 production has been associated to some inflammatory skin diseases such as atopic dermatitis and psoriasis." (PMID 34408754, 2021). "Mechanistically, local γδ T cell are one of the predominant producers of IL-22 in the skin and are thus implicated in the pathogenesis of psoriasis." (PMID 33003458, 2020). "In patients with moderate-to-severe psoriasis, treatment with apremilast was associated with significant reductions in plasma levels of interleukin (IL)-17F, IL-17A, IL-22, and TNF-α." (PMID 33178709, 2020). "Consistently, IL-22 is closely associated with psoriasis pathogenesis, modulating pathological events such as keratinocyte proliferation and upregulation of antimicrobial molecules such as S100A7, S100A8, and S100A9." (PMID 32917058, 2020). "For example, exposure to IL-17 and IL-22, interleukins, which are elevated in psoriasis, caused the expression of stem markers p63, CD44, CD29, and CD49f in keratinocytes in vitro due to activation of the RAC1/MEC/ERK/NF-κB pathway." (PMID 33240882, 2020). "Previous evidence showed that among the several cytokines that are pathogenic to psoriasis, IL-22 most likely promotes the proliferation of keratinocytes." (PMID 32076123, 2020). "Pro-inflammatory activity performed by IL-22 has also been associated with several inflammatory diseases such as psoriasis and atopic dermatitis." (PMID 33042126, 2020). "Several reports have also implicated the IL-22/IL-22Rα system in the pathogenesis of psoriasis and atopic dermatitis." (PMID 31781680, 2019). "Even neutrophils have been implicated as major producers of IL-22 and IL-17A and recent animal models have re-explored their role as effector cells in psoriasis pathophysiology." (PMID 31019502, 2019). "There is a variety of evidence, including data obtained from in vitro studies with skin-like organoid cultures, that support IL-22 as the main cytokine responsible for epidermal hyperplasia, a hallmark of psoriasis." (PMID 31019502, 2019). "IL-22 is a key pathogenic cytokine in psoriasis and the main mediator of IL-22 signaling is STAT331–33." (PMID 30894513, 2019). "In this model, a major role of the IL-23/IL-17/IL-22 axis has been demonstrated, with IL-22-deficient mice being resistant to psoriasis development induced by IMQ." (PMID 30581877, 2018). "The pathogenic role of IL-22 has previously been reported in certain autoimmune diseases, such as psoriasis." (PMID 30057583, 2018). "We added psoriasis-associated cytokines of Th1 (TNFα, IL-6, and IL-1α) and Th17 (IL-17 and IL-22) origin to N/TERT1 HEEs during the last three days of the air-liquid interphase culture." (PMID 28928444, 2017). "In general, the effects of IL-17 and IL-22 can be protective – as in the case of extracellular infections – as well as pathogenic – as in psoriasis, allergies, and other inflammatory diseases of the tissue." (PMID 30402605, 2017). "Tobacco smoke extract can induce Th17 differentiation and expression levels of IL-17 and IL-22, which are cytokines associated with the pathogenesis of psoriasis, in an in vitro analysis." (PMID 29232931, 2017). "For instance, low levels of IL-22 binding protein and high IL-22 concentrations are associated with worse inflammation in psoriasis." (PMID 29163483, 2017). "Remarkably, both populations express IL-22 and IL-17 in the skin of psoriasis patients and represent two hallmark cytokines in the immunopathology of psoriasis in mouse models and humans." (PMID 28303135, 2017). "In the last years, other cytokines such as IL-9, IL-17, and IL-22 have been implicated in the pathogenesis of inflammatory and autoimmune diseases affecting skin, such as psoriasis, for example." (PMID 28855908, 2017). "IL-22 is likely a beneficial cytokine in B. anthracis infection, but in chronic inflammatory conditions such as inflammatory bowl disease or psoriasis, IL-22 can have pathogenic consequences." (PMID 29059238, 2017).